RASAL1 (RAS protein activator like 1)
Description:
Probable inhibitory regulator of the Ras-cyclic AMP pathway. Plays a role in dendrite formation by melanocytes.
Synonyms: RASAL
Tractability: Antibody: its Gene Ontology location is reachable by antibodies, with high confidence; the Human Protein Atlas places it where antibodies can reach. PROTAC: ubiquitination databases record sites on it; its protein half-life has been measured.
Gene: Protein-coding gene on chromosome 12 (113,096,517 to 113,136,258, reverse strand). Ensembl gene ENSG00000111344.
Subcellular location (Human Protein Atlas): Cytosol; Plasma membrane; Cell Junctions
Pathways (Reactome):
Signal Transduction: Regulation of RAS by GAPs
Gene Ontology:
Molecular function: GTPase activator activity; phospholipid binding
Biological process: positive regulation of dendrite extension; regulation of intracellular signal transduction; signal transduction; cellular response to calcium ion; intracellular signal transduction; negative regulation of Ras protein signal transduction
Cellular component: cytosol; plasma membrane
Genetic constraint (gnomAD): Loss-of-function variants: 69 observed, 86.04 expected, observed/expected ratio (o/e) 0.8, 90% interval 0.66 to 0.98. The upper end of that interval is the gene's LOEUF score, 0.98, which puts it in group 4 of 6, group 1 being the genes least tolerant of losing a copy. Missense variants: 932 observed, 965.38 expected, observed/expected ratio (o/e) 0.97, 90% interval 0.91 to 1.02. Synonymous variants: 379 observed, 382.94 expected, observed/expected ratio (o/e) 0.99, 90% interval 0.91 to 1.08.
Homologues: Orthologues: chimpanzee RASAL1 (99% identical), macaque RASAL1 (91% identical), dog RASAL1 (90% identical), pig RASAL1 (89% identical), mouse Rasal1 (85% identical), rat Rasal1 (85% identical), guinea pig RASAL1 (85% identical), rabbit RASAL1 (84% identical), tropical clawed frog rasal1 (63% identical), Drosophila melanogaster RasGAP1 (29% identical), Drosophila melanogaster raskol (28% identical), Caenorhabditis elegans gap-2 (19% identical), and 2 more. Paralogues in human: RASA4 (49% identical), RASA4B (49% identical), RASA3 (32% identical), RASA2 (28% identical), NF1 (24% identical), RASAL2 (23% identical), DAB2IP (23% identical), RASA1 (21% identical), RASAL3 (18% identical).
Diseases named in the same sentence as RASAL1 in open-access papers:
RASAL1 is named in the same sentence as 56 diseases in open-access papers, as found by Europe PMC text mining. Sharing a sentence is not in itself a finding about the gene and the disease. The quoted sentences say what the papers report.
renal fibrosis (23 papers, 2015 to 2026). A final common manifestation of a wide variety of chronic kidney diseases characterized by glomerulosclerosis and tubulointerstitial fibrosis. "Hypermethylation of RASAL1, encoding an inhibitor of the Ras protein, is associated with the perpetuation of fibroblast activation and experimental renal fibrosis." (PMID 26137526, 2015). "In this study, renal fibrosis was again associated with RASAL1 hypermethylation and subsequent suppression." (PMID 26435749, 2015). "Moreover, the RAS protein activator-like 1 (RASAL1) encoded by Rasal1 inhibits renal fibrosis by switching off RAS activity." (PMID 35055027, 2022). "The RASAL1 gene encodes an inhibitor of the Ras protein and hyperglycemia is known to cause hypermethylation of RASAL1, which is associated with the perpetuation of fibroblast activation and renal fibrosis." (PMID 34769288, 2021). "In mouse models of renal fibrosis induced by unilateral ureteral obstruction and aristolochic acid I, RASAL1 suppression coincided with a preferential increase in HDAC3." (PMID 41624795, 2026). "Here, we identify histone deacetylase 3 (HDAC3) as a critical epigenetic suppressor of RASAL1 expression in FMT of renal fibrosis." (PMID 41624795, 2026). "Rasal1 and Klotho are uniquely methylated in renal fibrosis, where Rasal1 and Klotho have been revealed to play a role in fibroblast proliferation and ECM production." (PMID 36864460, 2023). "Low-dose hydralazine induces TET3 expression, which promotes demethylation of the RASAL1 promoter and results in the inhibition of renal fibrosis after ischemic injury." (PMID 35215236, 2022). "TGF-β1 induced the hypermethylation of the Rasal1 (Ras–Gap-like protein 1) promoter and decreased RASAL1 gene expression, thereby increasing fibroblast activation and fibrosis, resulting in renal fibrosis." (PMID 36012674, 2022). "Bone morphogenic protein 7 (BMP7) administration can increase Tet3 expression and reverse the Rasal1 promoter hypermethylation with the amelioration of renal fibrosis in UUO and DKD animal models." (PMID 35055027, 2022). "In the kidney, low dose HDZ prevents renal fibrosis through the demethylation of the Rasal1 promoter in a murine model of acute kidney injury." (PMID 32503264, 2020). "We conclude that RASAL1 promoter methylation is a therapeutic target and a biomarker of renal fibrosis." (PMID 25717475, 2015). "And second, circulating methylated RASAL1 promoter fragments is a possible biomarker for the severity of renal fibrosis." (PMID 26137526, 2015). "From this data we concluded that circulating Rasal1 promoter DNA fragments correlate with intrarenal Rasal1 promoter CpG island methylation, and possibly with extent of fibrosis in experimental renal fibrosis as it does in cancer patients." (PMID 25717475, 2015). "Rasal1 encodes a Ras-GTP inhibitor, and its promoter is hypermethylated in renal fibrosis." (PMID 40650152, 2025). "In addition, hypermethylation of these specific genes (such as RASAL1, Klotho, etc.)can also directly lead to severe renal fibrosis, suggesting that the steady-state imbalance of DNA methylation directly affects renal fibrosis progression." (PMID 36105187, 2022). "The key role of RASAL1 hypermethylation in renal fibrosis was further confirmed." (PMID 26137526, 2015). "In summary, our studies suggest that Hydralazine ameliorates experimental renal fibrosis through inducing de-methylation of aberrantly methylated Rasal1 (and additional genes as well) by Dnmt1 inhibition and by inducing the endogenous Tet3/Tdg de-methylation pathway." (PMID 25717475, 2015). "Renal fibrosis was inversely correlated with intrarenal RASAL1 mRNA expression levels and the degree of intrarenal RASAL1 promoter CpG island methylation correlated with the degree of renal fibrosis, irrespective of the underlying disease, validating previous studies." (PMID 25717475, 2015).
renal fibrosis (continued). "Fibroblast-specific Hdac3 knockout mice exhibited preserved RASAL1 expression, attenuated FMT, and reduced renal fibrosis compared to wild-type controls." (PMID 41624795, 2026). "For example, low-dose hydralazine induces promoter demethylation in the gene of RAS protein activator like 1 (RASAL1), and subsequently attenuates renal fibrosis in the context of AKI to CKD." (PMID 33737884, 2021). "Our study adds further evidence for the utility of RASAL1 methylation as a biomarker of renal fibrosis, which is not surprising as several transcriptional profiling studies revealed that RASAL1 expression is consistently decreased in kidney biopsies from patients with chronic kidney disease." (PMID 25717475, 2015).
thyroid cancer (13 papers, 2014 to 2024). "RASAL1 hypermethylation was associated with activation of the RAS signaling in thyroid cancer, hepatocellular cancer, and gastric cancer." (PMID 39032134, 2024). "They discovered RASAL1 gene-disabling mutations and promoter hypermethylation in thyroid cancer samples, predominantly FTC and ATC, suggesting the RASAL1 is a key TSG in thyroid cancer." (PMID 35626065, 2022). "Compared with normal human thyroid tissue, the RAS GTPase-activating protein gene, RASAL1, is commonly, but differentially, somatically mutated or hypermethylated in thyroid cancers." (PMID 31247975, 2019). "Sequence analysis of thyroid cancer samples for somatic mutations in RASAL1 predominantly identify mutations in FTC tumors." (PMID 31247975, 2019). "Underexpression of RASAL1 was associated with colorectal and gastric cancer progression while its overexpression suppressed the growth of gastric cancer cells and thyroid cancer cells." (PMID 39032134, 2024). "Moreover, germline RASAL1 variants may be relatively frequent in patients with apparently sporadic thyroid carcinoma with follicular features." (PMID 32906649, 2020). "For example, RASAL1 is a major tumor suppressor gene in thyroid cancer, which is frequently inactivated by hypermethylation and mutations." (PMID 29723302, 2018). "Ras protein activator like 1 (RASAL1) is a major tumor suppressor in thyroid cancer and its alterations can affect the MAPK pathway activity." (PMID 24662939, 2014). "Some deleterious mutations in RASAL1 were reported in follicular thyroid cancer (FTC) and anaplastic thyroid cancer (ATC) with in vitro confirmation of their oncogenic consequences, identifying RASAL1 for the first time as a tumor suppressor gene in a human cancer (thyroid cancer)." (PMID 39032134, 2024). "Among the 21 Rasal1‐Pten double‐KO mice, 42.9% (9/21) developed hyperplasia (6 in thyroid gland and 3 in both thyroid gland and uterus) and 57.1% (12/21) developed cancers, including 11 thyroid cancer and 1 lymphoma." (PMID 39032134, 2024). "This indicates a possible TSG role for both APC and RASAL1 in thyroid cancer development." (PMID 35626065, 2022). "Moreover, WES data indicate the presence of APC and RASAL1 gene alterations in various thyroid cancer subtypes." (PMID 35626065, 2022). "Therefore, abnormal RASAL1 gene expression may affect these pathways and thyroid cancer development." (PMID 35626065, 2022). "In thyroid cancer cells, PA2G4 inhibited proliferation, migration and invasion by increasing the expression of RAS protein activator like 1 (RASAL1)." (PMID 35526051, 2022). "The molecular pathogenesis of thyroid cancer involves genetic alterations in both oncogenes and tumor suppressor genes, as exemplified by BRAF and RAS for the former and PTEN and RASAL1 for the latter." (PMID 26716505, 2016). "RAS protein activator like 1 (RASAL1) is the negative modulator of the RAS signaling pathway that has been identified as a key TSG in thyroid carcinoma." (PMID 35626065, 2022). "Finally, RASAL1 displays MAPK- and PI3K-suppressing activities in multiple tumors, including thyroid cancer." (PMID 33096593, 2020). "In a large series of 155 patients with Cowden syndrome and thyroid cancer, 39 presented with PTEN germline mutations, while RASAL1 germline alteration (RASAL1, c.982C>T, R328W) was observed in two patients without PTEN mutations." (PMID 33218058, 2020). "RASAL1, a member of the RAS GAP family, has been reported to act as a major tumor suppressor gene that influences the proliferation and invasion of cancer cells by regulating the RAS/ERK signaling pathway in different cancer types, including gastric cancer and thyroid cancer." (PMID 37149929, 2023).
colon cancer (6 papers, 2016 to 2022). "Recently, results from colon cancer cells and xenograft tumor models have demonstrated that RAS protein activator-like 1 inhibits colon cancer cell proliferation by regulating LXRα/SREBP1c-mediated SCD1 activity." (PMID 35912181, 2022). "Compared to the mRNA and protein expression levels in the normal colonic epithelial cell line NCM460, RASAL1 has a low level of expression in multiple colon cancer cell lines, including LoVo, CaCo2, HCT-116, SW116 and SW480." (PMID 31847887, 2019). "Indicating RASAL1 as a promising therapeutic target for the elimination of tumor-initiating colon cancer cells." (PMID 31847887, 2019). "Reductions in RASAL1 expression were detected more frequently in advanced lesions than in small adenomas, suggesting that RASAL1 functions in the progression of benign colonic neoplasms." (PMID 33817145, 2019). "The results showed that the proliferation of colon cancer cells was significantly inhibited by RASAL1 overexpression." (PMID 31847887, 2019). "Taken together, we concluded that RASAL1 inhibited colon cancer cell proliferation via modulating SCD1 activity through LXRα/SREBP1c pathway." (PMID 31847887, 2019). "In order to understand the role of RASAL1 during the progress of colon cancer, we first determined the expression levels of RASAL1 in 27 pairs of colon cancer tissues and adjacent normal tissues using quantitative RT-qPCR." (PMID 31847887, 2019). "Taken together, we concluded that RASAL1 inhibited colon cancer cell proliferation in vitro and in vivo." (PMID 31847887, 2019). "Accordingly, down-regulated RASAL1 expression was detected more frequently in advanced lesions than in small adenomas, suggesting that RASAL1 functions in the progression of benign colonic neoplasms." (PMID 33817145, 2019). "After RASAL1 transfection for 24 h, the percentage of colon cancer cells in the G2/M phase increased (LoVo: 9.4–21.7%; HCT-116: 11.7–20.4%) compared to the control." (PMID 31847887, 2019). "We found that tumor growth suppression was abrogated in colon cancer cells xenografts where RASAL1 was overexpressed." (PMID 31847887, 2019). "In addition, overexpression of RASAL1 inhibited the cell cycle regulation protein expression in a dose-dependent manner and decreased tumor growth in xenograft nude mice models of colon cancer in vivo." (PMID 31847887, 2019). "Moreover, we found that the expression of SCD1 was obviously downregulated when the colon cancer cells were transfected with RASAL1." (PMID 31847887, 2019). "Next, we detected the expression level of RASAL1 in colon cancer cell lines." (PMID 31847887, 2019). "In view of the important role of lipid metabolism in colon cancer, we screened key regulator genes in lipid metabolism to comprehensively understand the effect of RASAL1 on colon cancer progression, and found that RASAL1 efficiently decreased protein expression of SCD1." (PMID 31847887, 2019). "Recent studies have confirmed that RASAL1 has an antitumor effect in many cancers, but its functional role and the molecular mechanism underlying in colon cancer has not been investigated." (PMID 31847887, 2019). "RASAL1 has a low level of expression in colon cancer tissues." (PMID 31847887, 2019). "In this study, an decreased in RASAL1 were identified in colon cancer tissue." (PMID 31847887, 2019). "We previously found that RASAL1 expression was specifically downregulated in colon cancers containing wild-type Ras and in gastric carcinoma, and this may be a mechanism of inducing wild-type Ras oncogenic activity." (PMID 29029395, 2017). "In addition, our also found that, RASAL1 could facilitate the proliferation and fatty acid synthesis of colon cancer cell lines." (PMID 31847887, 2019). "Since Ras as the upstream in the regulating of SREBP1c expression, RASAL1 as the RAS GTPase-activating protein, so we suggest whether RASAL regulate the SCD1 activity also via LXRα and SREBP-1 pathway in colon cancer." (PMID 31847887, 2019).
colon cancer (continued). "RASAL1 expression is decreased in many tumors, including thyroid cancer, gastric cancer, prostatic cancer and bladder cancer, but its functional role in colon cancer has not been investigated." (PMID 31847887, 2019).
gastric cancer (6 papers, 2017 to 2024). A primary or metastatic malignant neoplasm involving the stomach. "SRCIN1 has been reported to block ERK signaling, and RASAL1 can act as a tumor suppressor gene in gastric cancer through inactivation of the ERK pathway." (PMID 37149929, 2023). "In contrast, in gastric cancer overexpression of miR-130b-5p led to increased proliferation, migration and invasion, reportedly through its ability to target RAS protein activator like 1 (RASAL1)." (PMID 35597813, 2022). "Namely, miR-130b-5p has been shown to promote proliferation and migration in gastric cancer via targeting RASAL1, as well as in osteosarcoma via binding to TIMP2." (PMID 34805186, 2021).
acute kidney injury (5 papers, 2013 to 2025). Sudden and sustained deterioration of the kidney function characterized by decreased glomerular filtration rate, increased serum creatinine or oliguria. "Moreover, the study of renal disease models demonstrated that the hypermethylation of the RASAL1 promoter and consequently decreased transcription of this gene was associated with acute kidney injury (AKI) and chronic progressive fibrosis." (PMID 35806113, 2022). "It is therefore proposed that the use of epigenomic editors which activate antifibrotic genes, including RASAL1, KL, and IL-10, may represent a promising approach for the treatment of acute kidney injury and fibrosis." (PMID 40650152, 2025). "Hydralazine was shown to demethylate RASAL1 via reno-protective effects in a mouse model of acute kidney injury (AKI) with IRI." (PMID 36421409, 2022). "However, this region was never found to be methylated in acute kidney injury, which is associated with transient fibroblast activation and transient suppression of RASAL1 transcription." (PMID 23782569, 2013).
Cowden Syndrome (5 papers, 2019 to 2024). "Some germline alterations in RASAL1 were found in Cowden Syndrome patients presenting with FTC and germline variants in RASAL1 were suggested to confer susceptibility to BRCA." (PMID 39032134, 2024). "Another intriguing fact was the association of RAS protein activator like 1 (RASAL1) with Cowden Syndrome." (PMID 33218058, 2020). "Germline mutations in RASAL1 have been identified in differentiated thyroid cancer (DTC) and in patients with Cowden Syndrome characterized by both BC and DTC features." (PMID 32906649, 2020).
chronic kidney disease (4 papers, 2015 to 2025). Impairment of the renal function secondary to chronic kidney damage persisting for three or more months. "A seminal study in the field of epigenetics and chronic kidney disease (CKD), published in 2010, demonstrated that methylation of the promoter of Rasal1—a gene encoding a Ras inhibitor—by the DNA methyltransferase DNMT1 activates renal fibroblasts and promotes renal fibrosis." (PMID 40186651, 2025). "Due to the prominent functional contribution of RASAL1 promoter CpG island methylation to progression of chronic kidney disease, tools to specifically de-methylate RASAL1 should be developed and explored in the future." (PMID 25717475, 2015). "For this purpose we compared levels of circulating methylated RASAL1 promoter DNA fragments in patients with comparable stage of chronic kidney disease due to malignant arterial hypertension (HTN) with or without Dihydralazine treatment." (PMID 25717475, 2015).
Ureteral obstruction (4 papers, 2015 to 2026). Obstruction of the flow of urine through the ureter. "First, by using transgenic mice harboring transgenes for doxycycline-inducible RASAL1 overexpression, RASAL1 over-expression was demonstrated to normalize the increased intrinsic proliferative activity of fibrotic fibroblasts in these mice with unilateral ureteral obstruction." (PMID 26137526, 2015).
bladder cancer (3 papers, 2011 to 2021). "Further studies are needed to address the mechanisms that underlie the RASAL1 over-expression and epigenetic aberration in bladder cancer." (PMID 22140553, 2011). "As was mentioned in the results of massive BSP and RT-qPCR tests, RASAL1 methylation levels were significantly down-regulated, and the expression levels was dramatically increased in bladder cancer cells in 66.7% and 53.3%, respectively, of the patients with bladder cancer examined." (PMID 22140553, 2011). "However, the relationship between PITX1 and RASAL1 in bladder cancer has remained elusive." (PMID 32441304, 2020). "For instance, in prostate cancer and bladder cancer, PITX1 is expressed at low levels and suppresses tumorigenicity by downregulating the RAS pathway through the transcription target RASAL1." (PMID 34868397, 2021). "Surprisingly, RASAL1, the RAS signal terminator, was highly over-expressed and hypomethylation of the promoter was also observed in the majority of the examined bladder cancer tissues in our research." (PMID 22140553, 2011).